NAT8 (N-acetyltransferase 8 (putative))
Description:
Endoplasmic reticulum (ER)-membrane-bound lysine N-acetyltransferase catalyzing the N6-acetylation of lysine residues in the lumen of the ER in various proteins, including PROM1 and BACE1, using acetyl-CoA as acetyl donor. Thereby, may regulate apoptosis through the acetylation and the regulation of the expression of PROM1. May also regulate amyloid beta-peptide secretion through acetylation of BACE1 and the regulation of its expression in neurons. N(6)-lysine acetylation in the ER maintains protein homeostasis and regulates reticulophagy (By similarity). Alternatively, acetylates the free alpha-amino group of cysteine S-conjugates to form mercapturic acids. This is the final step in a major route for detoxification of a wide variety of reactive electrophiles which starts with their incorporation into glutathione S-conjugates. The glutathione S-conjugates are then further processed into cysteine S-conjugates and finally mercapturic acids which are water soluble and can be readily excreted in urine or bile.
Synonyms: ATase2; CCNAT; CML1; GLA; TSC501; Hcml1; TSC510
Tractability: Antibody: UniProt predicts a signal peptide or a membrane-spanning region. PROTAC: its protein half-life has been measured.
Gene: Protein-coding gene on chromosome 2 (73,640,723 to 73,643,229, reverse strand). Ensembl gene ENSG00000144035.
Subcellular location: Endoplasmic reticulum-Golgi intermediate compartment membrane; Endoplasmic reticulum membrane
Subcellular location (Human Protein Atlas): Endoplasmic reticulum
Pathways (Reactome):
Metabolism of proteins: Amyloid fiber formation
Gene Ontology:
Molecular function: L-cysteine-S-conjugate N-acetyltransferase activity; protein binding; protein-lysine-acetyltransferase activity; L-lysine N-acetyltransferase activity, acting on acetyl phosphate as donor; N-acetyltransferase activity; acyltransferase activity, transferring groups other than amino-acyl groups
Biological process: peptidyl-lysine N6-acetylation; positive regulation of gene expression; amyloid fibril formation; glutathione metabolic process
Cellular component: endoplasmic reticulum; endoplasmic reticulum membrane; endoplasmic reticulum-Golgi intermediate compartment; endoplasmic reticulum-Golgi intermediate compartment membrane; membrane
Genetic constraint (gnomAD): Loss-of-function variants: 0 observed, 0.12 expected, observed/expected ratio (o/e) 0, 90% interval 0 to 1.89. That is too few expected variants to judge how well the gene tolerates losing a copy. Missense variants: 357 observed, 299.04 expected, observed/expected ratio (o/e) 1.19, 90% interval 1.09 to 1.3. Synonymous variants: 131 observed, 119.18 expected, observed/expected ratio (o/e) 1.1, 90% interval 0.95 to 1.27.
Homologues: Orthologues: chimpanzee NAT8 (99% identical), macaque NAT8 (83% identical), pig NAT8 (63% identical), dog NAT8 (59% identical), mouse Nat8f3 (58% identical), mouse Nat8f6 (58% identical), mouse Nat8f7 (57% identical), rat Nat8f3 (54% identical), tropical clawed frog nat8.7 (37% identical), tropical clawed frog nat8.5 (36% identical), tropical clawed frog nat8 (34% identical), zebrafish nat8 (34% identical), and 2 more. Paralogues in human: ASPNAT (32% identical), NAT14 (17% identical).
Diseases named in the same sentence as NAT8 in open-access papers:
NAT8 is named in the same sentence as 32 diseases in open-access papers, as found by Europe PMC text mining. Sharing a sentence is not in itself a finding about the gene and the disease. The quoted sentences say what the papers report.
chronic kidney disease (6 papers, 2014 to 2021). Impairment of the renal function secondary to chronic kidney damage persisting for three or more months. "N-delta-acetylornithine was previously associated with NAT8, a gene correlated with creatinine levels and chronic kidney disease in AA." (PMID 33661917, 2021). "This situation holds for genes such as MPC2, associated with schizophrenia, SYCP3, with azoospermia, and NAT8, with chronic kidney disease." (PMID 32392208, 2020). "A missense mutation in NAT8 (rs13538), a known susceptibility locus for chronic kidney disease, was significantly associated with N-acetylornithine and N-acetyl-1-methylhistidine levels." (PMID 24625756, 2014). "There are reported GWAS associations between ATase2/NAT8 and chronic kidney disease in humans." (PMID 33846551, 2021). "Furthermore, mutations in the NAT8 gene have been found to be associated with chronic kidney disease." (PMID 25057902, 2014). "In addition, four potential disease-associated paths were identified, including two direct longitudinal predictive relationships: NAT8 with N-acetylornithine, N-acetyl-1-methylhistidine and incident chronic kidney disease, and TREH with trehalose and incident diabetes." (PMID 24625756, 2014).
progeria (3 papers, 2022 to 2025). "Gene duplication events involving 3q25.31 (harboring AT-1/SLC33A1) and 2p13.1 (harboring ATase1/NAT8B and ATase2/NAT8) are associated with autism spectrum disorder with intellectual disability and progeria-like dysmorphism." (PMID 40930841, 2025).
schizophrenia (3 papers, 2020 to 2023). A major psychotic disorder characterized by abnormalities in the perception or expression of reality. "We replicated one of the three findings of the previous CSF study, which was brain ethylmalonate’s causal effect on schizophrenia, while the other two (N-delta-acetylornithine’s causal effect on cognitive performance and schizophrenia) were not replicated due to its pleiotropic signal at NAT8." (PMID 37333177, 2023).
Hypertension (2 papers, 2008 to 2024). The presence of chronic increased pressure in the systemic arterial system. "The diversity of NAT8 5' upstream region (π/bp = 0.00320) exceeded up to 10 times the variation in the NAT8 genic region (π/bp = 0.00037) as well as the average variation (π/bp = 0.00040) for the promoters of 29 reference genes associated with hypertension." (PMID 18402670, 2008). "We further tested the association of NAT8 upstream SNPs with the reduction of kidney function as a consequence of essential hypertension using an Estonian cohort of long-term hypertension patients without and with hypertensive nephropathy." (PMID 18402670, 2008).
kidney damage (2 papers, 2008 to 2023). "Variants in NAT8, and CELF2 were associated with microalbuminuria, MUC1, and rs1077216 with UACR and AS3MT with kidney damage (p < 0.001)." (PMID 37446387, 2023). "The NAT8 promoter SNPs were targeted with pilot quantitative association studies for blood pressure (n = 137, healthy unrelated individuals) and for the index of kidney function – estimated glomerular filtration rate (eGFR; n = 157 hypertensives with and without nephropathy)." (PMID 18402670, 2008).
kidney failure (2 papers, 2014 to 2025). An acute or chronic condition that is characterized by the inability of the kidneys to adequately filter the blood. "In line, a study reported that NAT8 variants (encoding hepatic and renal acetyltransferase) caused an increase in levels of N-acetylated amino acids, which were associated with an increased risk of kidney failure." (PMID 40613013, 2025). "Although the exact function of NAT8 is unknown, it has recently been shown that NAT8 is associated with detoxification pathways and exerts a protective effect towards both elevated blood pressure and the risk of kidney failure." (PMID 25057902, 2014).
colon cancer (1 paper, 2024). "It has been reported that NAT8 is regulated by FDFT1 and promotes colon cancer cell proliferation in vivo and in vitro." (PMID 38517387, 2024).
colonic adenocarcinoma (1 paper, 2023). "Accumulation of NAT8 reduces the level of reactive oxygen species and has an inhibitory effect on colonic adenocarcinoma." (PMID 37496049, 2023).
diabetic kidney disease (1 paper, 2021). Progressive kidney disorder caused by vascular damage to the glomerular capillaries, in patients with diabetes mellitus. "Although NAT8 gene has not been linked with T2DM macrovascular complications before, it is considered to be a susceptibility locus for diabetic kidney disease." (PMID 33430853, 2021).
kidney cancer (1 paper, 2025). Primary or metastatic malignant neoplasm involving the kidney. "NAT8 expression has been shown to be regulated by methylation, and it has been connected with the infiltration of cancer-associated fibroblasts in kidney cancer (34630525)." (PMID 40373089, 2025).
renal carcinoma (1 paper, 2024). A carcinoma arising from the epithelium of the renal parenchyma or the renal pelvis. "The expression of FUCA1, NAT8 and SMIM24 in renal carcinoma cell lines is lower than those in renal tubular epithelial cells and suggests a better prognosis." (PMID 38517387, 2024).
cancer (6 papers, 2019 to 2025). A tumor composed of atypical neoplastic, often pleomorphic cells that invade other tissues. "The 13 overexpressed genes were reported to play a role in RCC: PAX2, NAT8, GBA3, SLC22A2 other cancer types: AOC1, HAO2, TMEM27, cell death (NPR3) or kidney metabolism: TMEM171, CYS1." (PMID 31150395, 2019).
kidney disease (5 papers, 2008 to 2024). "Kidney disease–associated NAT8 variants influenced not only NAT8 levels but also serum acetyl amino acid levels." (PMID 36787250, 2023). "It has been demonstrated that NAT8 was associated with kidney disease." (PMID 34630525, 2021). "Our results confirm previously identified associations of NEMG (NAT8, GATM, SLC22A2, WDR72, NOS3, AGXT2 and CPS1) with kidney disease and kidney function, providing new information that expands these associations to other kidney disease biomarkers." (PMID 38858654, 2024).
tumor (4 papers, 2021 to 2025). "The downregulated genes (DEPTOR, DPEP1, NAT8, and SUSD2) in the tumor and thrombus were associated with a worse survival rate when the gene was less expressed in the tumor, and the same correlation was observed for the upregulated genes (PLOD2 and SLC7A5)." (PMID 37328520, 2023). "Meanwhile, a higher tumor T stage was accompanied by reductions of RNA expression levels of NAT8, TINAG, and SLC17A1." (PMID 34630525, 2021). "Decreasing RNA expression levels of NAT8, TINAG, and SLC17A1 were associated with lower tumor grade of KIRC." (PMID 34630525, 2021). "Among these six hub genes, DEPTOR, DPEP1, NAT8, and SUSD2 were expressed at their highest levels in normal tissues, whereas PLOD2 and SLC7A5 were expressed at their highest levels in tumor thrombi." (PMID 37328520, 2023). "Furthermore, LRP2, NAT8 and ACE2, have been shown to modulate the tumor microenvironment of RCC, a critical factor influencing the response of antiangiogenic drugs and immunotherapy." (PMID 40373089, 2025). "DNA methylation levels of NAT8, TINAG and SLC17A1 was accompanied by an increasing tumor T stage." (PMID 34630525, 2021). "In particular, no relevant study identified the biological role of NAT8 in CAFs-mediated tumor microenvironment alteration." (PMID 34630525, 2021).
NAT8 also shares sentences with these, for which no sentence is quoted: diabetes (2 papers); Intellectual disability (2); proteopathy (2); Alzheimer disease (1); autism (1); autism spectrum disorder (1); Azoospermia (1); diabetic neuropathy (1); essential hypertension (1); heart disease (1); hypertensive nephropathy (1); iminoglycinuria (1); infection (1); injury (1); ischemic stroke (1); pulmonary hypertension (1); renal tumors (1); Type 2 diabetes (1).